VDR (vitamin D receptor)
Diseases named in the same sentence as VDR in open-access papers (continued):
Sharing a sentence is not in itself a finding about the gene and the disease.
tumor (continued). "Expression of the VDR correlated positively with ER status (p = 0.0227), with a higher percentage of VDR-positive cases among the ER-positive tumours - 74.2% (46 out of 62 cases)." (PMID 20831823, 2010). "There are some studies showing higher levels of VDR in tumour tissues, but this discrepancy can be attributed to the use of different evaluation techniques." (PMID 20831823, 2010). "Those tumours with HF differentiation were characterised by high expression of both nuclear VDR and nuclear β-catenin, particularly within the aberrant follicles." (PMID 18213391, 2008). "In contrast, all BCCs with low VDR expression and detectable nuclear β-catenin were characterized as infiltrative tumours." (PMID 18213391, 2008). "The VDR gene is subjected to complex transcriptional regulation: Wilm's tumour suppressor, Zeb-1, Cdx-2 and Sp1 transcription factors as well as protein kinase A induce VDR expression." (PMID 15770204, 2005). "We showed that inactivation of PTEN and VDR in PECs promotes tumor aggressiveness." (PMID 41957119, 2026). "Additionally, high-dose UVA triggered activation of p38 MAPK, upregulation of TNFα, and the regulatory signaling molecule Connective Tissue Growth Factor (CTGF) mRNA expression, while transcription of tumor-suppressors VDR, and P2RX7 were downregulated." (PMID 40328921, 2025). "It is currently hypothesized that functional VDR expression is essential for the anti-tumor effects of 1,25(OH)2D3.." (PMID 41282147, 2025). "These polymorphisms may also influence VDR expression levels in HNC tissues, potentially amplifying or dampening the anti-tumor effects of vitamin D supplementation, thus shaping individual responses to therapy and survival outcomes." (PMID 40218858, 2025). "Additionally, calcitriol inhibits tumor progression and enhances survival, particularly in tumors exhibiting high vitamin D receptor (VDR) expression." (PMID 40732958, 2025). "It has been observed that VDR expression in tumor stromal fibroblasts predicts a better clinical outcome, reinforcing the hypothesis that the protective effects of vitamin D are not limited to cancerous epithelial cells." (PMID 41301826, 2025). "Finally, VDR was also found to inhibit activation of hepatic stellate cells into pro-tumor CAFs in hepatocellular carcinoma." (PMID 41374952, 2025). "The findings that lower VDR expression is linked to a worse prognosis in TNBC, along with the inverse relationship between VDR expression and tumor aggressiveness, suggest that VDR may be a key factor in determining outcomes in this subtype." (PMID 39968442, 2025). "VDR plays a pivotal role in tumorigenesis and tumor development across multiple malignancies." (PMID 40872626, 2025). "Clearly, VDR expression, based on this study's findings, behaved as an oncogene not only through its clinicopathological correlations but also through its correlation with established biological pathways of tumorigenesis and tumor progression." (PMID 39963174, 2025). "High VDR expression in stromal fibroblasts generally correlates with better outcomes, suggesting that even patients with low VDR-expressing tumor cells might benefit from VDR agonists if their stromal cells are adequately expressing VDR." (PMID 41020251, 2025). "Furthermore, our database contains receptors including ESR1, FGFR2, and VDR, which are recognised for their roles in cellular responses and tumour development." (PMID 40754672, 2025). "In addition, VDR expression was increased in PTC tissues compared with matched adjacent non-tumor tissues at the mRNA and protein levels." (PMID 38639057, 2024). "In the context of our study, impaired VDR signaling pathway and decreased 1,25(OH)2D levels within tumor microenvironment may coexist to limit its antitumor effect in patients with LNM, even if the serum 25(OH)D level was high." (PMID 37991208, 2024).
tumor (continued). "The expression of the VDR is associated with the presence of several immune cell types, including B cells, CD8+ T cells, CD4+ T cells, macrophages, neutrophils, and dendritic cells, as well as the purity of tumor cells in CESC." (PMID 39268267, 2024). "Interestingly, subjects with distinctly higher VDR-IRS in the tumor cell cytoplasm than in normal lobules had RCB-I more frequently than RCB-II or RCB-III." (PMID 39411136, 2024). "Moreover, it was shown that the expression of VDR was sequentially upregulated from normal to a well-differentiated tumor while decreasing in poorly differentiated tumor." (PMID 38372868, 2024). "For example, there could be a greater impact on genes regulated by VDR related to angiogenesis, invasion, and metastasis (e.g., HIF1α and IL-8) compared with genes that influence tumor initiation (i.e., malignant transformation) (e.g. MYC and RB)." (PMID 39705237, 2024). "The GG genotype confers an mRNA molecule with lower transcriptional activity, resulting in lower abundance of VDR and thereby a weaker antiproliferative effect, which in turn may explain the faster tumor growth and larger tumor size upon discovery." (PMID 38351438, 2024). "The opposite outcomes for risk and survival in our PLCO analyses could also suggest differential inhibitory effects of vitamin D/Gc isoform on tumor initiation vs. growth, invasion, or metastasis via vitamin D receptor (VDR) response elements." (PMID 39705237, 2024). "Cytoplasmic VDR staining is inversely correlated with tumor staging, nodal status, and the AJCC stage groups, suggesting that loss of cytoplasmic VDR may be a prognostic factor for bladder SCC." (PMID 38265102, 2024). "The role of VDR in tumor progression and tumor immunity remains to be elucidated." (PMID 38639057, 2024). "Nuclear VDR expression is significantly higher in tumor samples than cytoplasmic VDR." (PMID 38265102, 2024). "On the other hand, the prognostic significance of VDR expression in tumor cells and stroma variest." (PMID 38600588, 2024). "However, there is also increasing evidence to support an oncogenic role for VDR in tumor progression." (PMID 37880985, 2024). "The tumor microenvironment (immune cell infiltration, surrounding breast lobules, and ducts) should also be considered because the expression of VDR in these compartments could also play a role." (PMID 39411136, 2024). "Therefore, low intestinal VDR expression levels, and low plasma VitD levels in normal individuals or patients with intestinal diseases promote neoplasm development." (PMID 38329439, 2024). "Especially in KICH and TGCT, VDR expression increased in the early stage but decreased in the late stage, which may be attributed to the compensatory role of VDR in early tumor progression and the lost of compensatory effect in the advanced stage." (PMID 38639057, 2024). "The expression of VDR in BC cells and the tumor microenvironment could be a new prognostic factor for BC after NAC." (PMID 39411136, 2024). "Activation of VDR pathway was a promising anti-tumor therapy strategy." (PMID 38600588, 2024). "The results from the present studies indicate that VDR may participate in regulating the proportion of immune and stromal cells in tumor microenvironment." (PMID 38639057, 2024). "This may be due to either reduced expression of VDR or decreased local availability of 1,25(OH)2D within the tumor microenvironment." (PMID 37991208, 2024). "There is also one study based on in vitro and animal models indicating that unliganded VDR may stimulate tumor growth." (PMID 38612962, 2024). "Moreover, we found that the VDR levels correlated with the patients’ clinical and pathobiological tumor parameters." (PMID 36902107, 2023). "So far, evidence on the crosstalk between the LCA/VDR axis and tumor cell immunity is sparse." (PMID 38203175, 2023). "VDR is upregulated in many tumor cells of different types of cancers." (PMID 37520529, 2023).
tumor (continued). "The development of VDR agonists that exert anti-fibrotic and anti-tumor functions in the liver is ongoing and may represent a promising strategy for NAFLD disease progression." (PMID 37175993, 2023). "Similarly, another recent study showed that a combination of VDR and gemcitabine enhanced PC therapy through modulation of the tumour microenvironment." (PMID 37509236, 2023). "VDR signaling is thought to promote anti-tumor immunity by inhibiting the Wnt-beta catenin pathway." (PMID 37175993, 2023). "Additionally, the VDR protein expression was analyzed by immunofluorescence and immunohistochemical staining in tumor biopsies classified as poorly, moderately, and well-differentiated." (PMID 36902107, 2023). "Both vitamin D metabolism and the actions of the VDR would therefore be reduced, which could favor tumor progression." (PMID 37627104, 2023). "It has also been observed that the lack of VDR causes an increase in tumor growth and the development of metastases." (PMID 37371857, 2023). "This may be related to a lower proliferative state and the G1-phase arrest of tumor cells with high expression of VDR." (PMID 36986255, 2023). "Additionally, VDR overexpression prevented β-catenin accumulation in the nucleus in vitro and suppressed tumour development in vivo." (PMID 37046222, 2023). "Furthermore, the confirmation that the vitamin D receptor (VDR) is present in many human tissues confirmed the physiopathological significance of vitamin D in various human tumours." (PMID 37299554, 2023). "The active form of VD, 1α,25-(OH)2D3, inhibits tumour growth; additionally, through binding to the VD receptor (VDR), it plays a transcriptional regulatory role by facilitating the combination of its DNA-binding domain with VD response elements in target genes." (PMID 36846715, 2023). "In addition, vitamin D functioning through its receptor VDR is regulated by ncRNAs and, most importantly, VDR itself influences the expression of oncogenic and tumor suppressor lncRNAs." (PMID 36979019, 2023). "According to several studies, the amount of VDR present might be predictive of malignant disease outcomes, as studies have shown that the higher the VDR expression in tumor tissue, the better the prognosis of patients." (PMID 37960224, 2023). "It has also been shown that the addition of vitamin D analogs could potentiate the antitumor effect of the AI anastrozole in MCF7 tumor bearing mice via regulation of both VDR and ER signaling." (PMID 37583424, 2023). "Furthermore, nude mice injected with VDR-overexpressing SW480 cells revealed suppression of tumour growth and decreased expression of β-catenin, cyclin D1 and LEF-1." (PMID 37046222, 2023). "Moreover, VDR can upregulate the expression of the tumour-suppressor gene E-cadherin by targeting the Wnt/β-catenin pathway." (PMID 37561808, 2023). "Overall, our findings suggest that JAG1 may affect the transcription of PDL1 by regulating the expression of VDR, leading to tumor immune escape, promoting tumor cell survival, and shortening patient survival." (PMID 38022677, 2023). "Therefore, the VDR reading frame was cloned from primary HNC tumor cells and stably expressed VDR-GFP in the HNCUM-02T or HNC FaDu cells." (PMID 36902107, 2023). "The results showed that tumour location, race, pathological type, and cut-off value did not affect the association between VDR expression and patient OS but that tumour type did (P<0.05)." (PMID 37561808, 2023). "A role of VDR in the activity of CAFs in tumor progression was highlighted." (PMID 37175993, 2023). "In addition, our aim was to investigate possible associations of VDR and CYP24A1 expression and tumour characteristics, as well as patient outcomes." (PMID 36362766, 2022).
tumor (continued). "1,25(OH)2D3 not only directly influences tumor development via the vitamin D receptor but also indirectly modulates this process through crosstalk with the tumor microenvironment, different immunological pathways, and the functional interplay between the vitamin D and androgen receptors." (PMID 35326710, 2022). "Moreover, it was observed that EAC exhibits VDR expression, and as the tumor dedifferentiates, the expression level of VDR also decreases." (PMID 36142861, 2022). "A low VDR expression in primary tumours is correlated with the metastatic spread of tumour cells." (PMID 36362766, 2022). "Defective VDR signalling would therefore be associated with reduced numbers of immunocytes, which however, unlike the tumour, would retain sensitivity to vitamin D3." (PMID 35445563, 2022). "Numerically, the attached table shows VDR expression ratios for each tumor type." (PMID 35884356, 2022). "In combination with the Pirc/+ mutation, VDR loss did not enhance tumor multiplicity, growth, or progression in the colon or small intestine." (PMID 35662320, 2022). "In animal models, where tumour VDR signalling was apparently defective, vitamin D3 administration decreased survival and increased metastases, associated with downregulation of Th‐1 cells and INFG gamma and upregulation of MDSCs and TGFB and upregulation of transcription of Tregs and Th‐2 cells." (PMID 35445563, 2022). "For example, there was a tendency toward a lower risk of a VDR-negative tumor, when high levels of vitamin D were compared to low (OR: 0.72, 95% CI: 0.43–1.21)." (PMID 36014861, 2022). "The functional polymorphisms located in this region may affect the function of VDR by regulating mRNA stability and protein translation efficiency, influencing the effect of vitamin D on tumor inhibition." (PMID 36364930, 2022). "One study has demonstrated that calcitriol-mediated antiproliferative effects on tumor-derived endothelial cells (TDEC) are VDR dependent and that loss of VDR in knockout models can lead to an increase in HIF-1α, VEGF, Ang1, and PDGF-BB levels and subsequent abnormal tumor angiogenesis." (PMID 35406562, 2022). "In concordance with our findings, Larriba and colleagues found that VDR loss does not impact tumor number in either the small intestine or colon of VDR null ApcMin/+ mice." (PMID 35662320, 2022). "Furthermore, the knockdown or overexpression of VDR resulted in an increased or decreased proliferation and a decreased or an increased differentiation, respectively, indicating a tumor-suppressor role of VDR in DTC." (PMID 35099410, 2022). "There is a growing literature on tumor research on potentially effective complementary therapies to oncotherapy, such as the role of vitamin D through its antitumor gene-modifying effect on VDR." (PMID 35884356, 2022). "In addition, there is a theory that vitamin D binds to VDR and directly induces cell cycle arrest, thereby inhibiting tumor cell proliferation." (PMID 35982094, 2022). "Critical factors are the integrity of tumour cell VDR signalling and perhaps dosage." (PMID 35445563, 2022). "Notably, the activation of PSCs into tumor-promoting CAFs requires the upregulation of autophagy as well as other stimuli, such as vitamin D receptor (VDR) signaling." (PMID 35727403, 2022). "However, immunohistochemistry of a total of four TMA samples from two tumor blocks revealed significant, diffuse VDR expression of the tumor cells." (PMID 35884356, 2022). "Previous in vitro studies on several tumor types, including CRC, have shown that the vitamin D active form, 1α,25-dihydroxyvitamin D3 [1,25(OH)2D3] (calcitriol), is able to promote cell differentiation and inhibit tumor invasion and proliferation upon binding to its receptor VDR." (PMID 35681576, 2022). "However, the VDR pattern of different tumor types is a less studied area in the case of childhood malignancies." (PMID 35884356, 2022).
tumor (continued). "Then we investigated whether VDR suppresses tumor growth in vivo using a xenograft tumor model by subcutaneous injections of K1 cells into the flank of SCID mice (n = 6 for each group)." (PMID 35099410, 2022). "Moreover, the oncogenic role of AR, ER, GR, PPAR and VDR in tumor-supporting cells is well characterized." (PMID 36142861, 2022). "These opposing effects of vitamin D3 might be reconciled by the postulate of tumour VDR inhibiting a pro‐angiogenic factor secreted by the tumour." (PMID 35445563, 2022). "The rate of VDR expression differed significantly between tumor types (p < 0.0001)." (PMID 35884356, 2022). "Additionally, however, a semi-quantitative analysis of the immunohistochemical reaction showed a higher mean number of VDR immunopositive cells in the tumor-unchanged tissue." (PMID 36014877, 2022). "Collectively, a low VDR expression and the alteration of vitamin D catabolism may contribute to tumour progression and the metastatic process." (PMID 36362766, 2022). "However, this is an indirect effect of vitamin D3 and would appear dependent on intact intra tumour VDR signalling." (PMID 35445563, 2022). "Additionally, we found that poorly differentiated tumours had a trend towards having a low VDR expression." (PMID 36362766, 2022). "VDR is a member of the steroid/thyroid hormone receptor family that regulates biological processes including cell proliferation, differentiation, apoptosis, tumor invasion, and angiogenesis in vivo." (PMID 36440356, 2022). "VDR, as a transcription factor, is one of the most studied tumor suppressor genes." (PMID 33390783, 2021). "Sherman and collaborators discovered that the VDR is expressed in the stroma from PC cells and acts as a “master” transcriptional regulator of pancreatic stellate cells, thereby resulting in induced transcriptional reprogramming of tumor stroma in PAAD." (PMID 34335699, 2021). "This may be related to a lower proliferative state and G1-phase arrest of high VDR-expressing tumor cells." (PMID 34836039, 2021). "The serum level of iPTH was correlated with serum Ca (p<0.001, rs=0.685), alkaline phosphatase (ALP) (p<0.001, rs=0.802), phosphorus (P) (p<0.001, rs=-0.525) and tumor diameter (p<0.001, rs=0.570), as well as the expression levels of VDR (p=0.009, rs=-0.403) and PRUNE2 (p=0.009, rs=0.401)." (PMID 34054720, 2021). "However, significantly higher VDR expression as a potential additive effect of the calcitriol and aPPD combination led to tumor growth suppression." (PMID 34199743, 2021). "The CD3+ cell infiltration was higher in patients with high VDR expression in tumor stromal cells." (PMID 34572935, 2021). "IPA analysis of these DEGs identified a link between UPR/autophagy and tumor VDR status." (PMID 34069442, 2021). "In addition, vitamin D receptor (VDR) ligands promote the transition from activated to quiescent pancreatic stellate cells (PSCs), which lowers the secretion of tumor-promoting cytokines from these cells." (PMID 34572947, 2021). "Altogether, above data highlight the importance of nuclear receptor signaling in melanocytes driven by VDR and its principal heterodimer partners RXRα and RXRβ in the regulation of melanocyte homeostasis and melanomagenesis in the skin and tumor microenvironment." (PMID 34692525, 2021). "Additionally, a recent report states that VDR restricts stemness and chemotherapy resistance by regulating SOX2, a factor that maintains tumor-initiating cells, and is associated with poor prognosis." (PMID 34867333, 2021). "Another attempt of stromal remodeling to increase chemotherapeutic delivery took advantage of the overexpression of the vitamin D receptor, which according to a mice model, serves as a transcriptional master regulator of the tumor stroma in this tumor entity, mainly by affecting PSCs." (PMID 34680101, 2021). "It must also be noted that VDR is considered as a tumor suppressor in cutaneous carcinogenesis." (PMID 34206371, 2021).